IL2 (interleukin 2)
Diseases named in the same sentence as IL2 in open-access papers (continued):
Sharing a sentence is not in itself a finding about the gene and the disease.
infection (continued). "Low-dose IL-2 administration induces many of the Treg responses observed during infection." (PMID 28815218, 2017). "V3000 infection uniquely modulated several inflammatory signaling pathways such as IL-2, IL-4, IL-8, IL-9, IL-12 and IL-17A along with the unfolded protein response, gap junction signaling, crosstalk between DCs and NKCs, interferon and JAK/Stat signaling pathways." (PMID 28446152, 2017). "Furthermore, immunomodulatory effects of AMP-B became manifest upon exposure to cytokines such as IL-2 and IL-18, a situation that likely occurs during the course of infection and transformation." (PMID 28608807, 2017). "Thus, MC appear to be able to control CD25+ILC2 expansion in the lung during the infection via IL-2." (PMID 28090087, 2017). "In addition, stimulated CD4 T cells from infected animals produced less IFN-γ and IL-2 at an early time point of infection (21 p.i.)compared to control CD4 T cells." (PMID 28114324, 2017). "CD28 is the classic positive co-stimulatory receptor that, acting in conjunction with the T cell receptor (TCR), induces T cells to undergo proliferation and to produce cytokines such as interferon gamma (IFN-γ) and interleukin-2 (IL-2) that are critical in controlling infection." (PMID 26786705, 2016). "MTB-specific cells may be lost early in HIV infection and IL-2-secreting cells may be more vulnerable to infection with HIV." (PMID 26756579, 2016). "The cloning and sequence analysis of hamster genes related to infection with L. donovani in this animal model was described, revealing a non-polarized immune response profile characterized by an increase in expression of IL-2, IL-12, IFN-ɣ, TNF, IL-10 and TGF-β genes." (PMID 27350537, 2016). "Despite notable differences in IL-2 and IL-17 responses induced by nApa and rApa-booster regimens post-challenge, a similar degree of protection was observed with two booster vaccines in a 6-week infection experiment." (PMID 27173443, 2016). "The precise cocktails of innate cytokines that most efficiently activate NK cells in response to any given pathogen, and how these cytokines synergize with adaptive responses, such as IL-2 and antibody to optimize the initial response to infection, are poorly described." (PMID 27047490, 2016). "Whether the presence of low dose IL-2 enhanced the level of integration and infection observed in resting CD4+ T-cells is unclear." (PMID 27383184, 2016). "IL-2-/IFN-γ co-expressing CD4 T cells decreased during the course of infection." (PMID 27760221, 2016). "However, this RT increase was modest compared to the high RT production observed following infection of T-cells activated with PHA/IL-2." (PMID 27383184, 2016). "Intracellular levels of IL-2 were hardly detected during a primary infection (black histograms)." (PMID 26989699, 2016). "Reciprocally, treatment of macaques with IL-2 and G-CSF before infection led to the depletion of Th17 cells, reduction of the ratio between Th17 and Treg cells, and higher viral loads for 6 months after infection." (PMID 26568963, 2015). "Uninfected mice treated with the same regimen of IL-2 complexes survived more than 30 days and remained healthy, indicating the IL-2 complex treatment targeted detrimental cells that were only present during infection." (PMID 25764512, 2015). "NK cells have been recognized as a key link between innate and acquired immune response and it has also been recognized that T cells play a critical role in NK cell activation by secreting IL2, which allows NK cells to productively respond to a number of stimuli during infection." (PMID 25706946, 2015). "In cleared infections, IL-2 secreting CD4+ T-cells predominate." (PMID 25729380, 2015). "Specifically, TNF-α, GM-CSF, MIP-1α, IL-1α, IL-1β, IL-2, IL-3, IL-12p40, IL-12p70, and IL-17 levels were significantly reduced in UV-12 animals compared to vehicle control treated mice at both the 72 and 96 h post infection time points." (PMID 25984714, 2015).
infection (continued). "In addition, the aerosol boosting using γ-irradiated BCG three times successively induced antigen-specific CD4+ T cells that were IFN-γ+TNF-α+IL-2+, which were maintained until at least 10 weeks post-infection." (PMID 26509812, 2015). "Indeed, expansion of IL-2-/- OT-1 CD8+ T cells during infection is comparable with that of wild-type OT-1 cells in the primary response but show profound defect in the secondary response." (PMID 25962156, 2015). "However, studies in mice have demonstrated altered cytokine profiles over the course of infection, starting with a pro-inflammatory Th1 response, and switching to a Th0 balance (equal amounts of IL-2 and IL-4 production) during chronic infection." (PMID 24918450, 2014). "The levels of TNF-α, IL-12p70, and IL-2 were lower during infection." (PMID 24741587, 2014). "Likewise, the proportion of CD4+ cells that individually express IFN-γ, TNF-α and IL-2 remained high eight-weeks post infection." (PMID 25500571, 2014). "For instance, IL-2 signaling via Stat5 potently inhibits Th17 cell development, and therefore by limiting IL-2 availability Treg cells can actually promote Th17 cell differentiation and immune responses to infection with the fungal pathogen Candida albicans." (PMID 25076948, 2014). "Treg-mediated IL-2 deprivation is a reason of T cell-suppression during infection." (PMID 24887408, 2014). "Furthermore, resting CD4+ T cells did not produce CXCL10 in response to Sendai virus infection, whereas the IL2/PHA-activated CD4+ T cells responded to this infection in a manner similar to the IL2/PHA-activated PBMCs." (PMID 24404168, 2014). "Similarly, the production of the chemokine, MIP-1β, peaks at day 7 post infection, whereas the peak IL-2 response was detected 14-28 days post-infection, suggesting a maturation of an effector cell response." (PMID 25397604, 2014). "Transcripts of IL-2 and IFNγ appear to be less abundant in the later stages of infection, which is consistent with the Th2-type response and concurrent suppression of Th1-type cytokine levels observed in the gastric lymph node during O. ostertagi infection of cattle." (PMID 24712712, 2014). "Early studies using animal models showed that infection with Mtb HN878 induced Type I interferons, and this coincided with decreased induction of proinflammatory cytokines such as TNF-α, IFN-γ and IL-2, reduced T cell activation and increased susceptibility to infection." (PMID 24831696, 2014). "BCG-TB1860 infection extinguished IL-2 secretion by BMDC almost completely." (PMID 24945624, 2014). "BCG-TB1860His infection also resulted in similar reduction of IL-2, IL-6, IL-12p40 and TNF-α." (PMID 24945624, 2014). "By day 7 post-infection the mean IL-2 levels had increased in the all virus-infected groups compared with the control group, while on day 14 the mean IL-2 levels in the 20 mg/kg PCA- and amantadine-treated groups were significantly higher than that of the untreated group (P<0.01)." (PMID 25337912, 2014). "The role of some cytokines such as IL-2 may thus be important only with particular pathogens and efforts should therefore be made to diversify the models of infection." (PMID 24376448, 2013). "T lymphocytes of volunteers successfully infected with either NF135.C10 or NF54 showed similarly increased IFN-γ, tumor necrosis factor, and interleukin 2 recall responses 35 days after infection and the same kinetics for both homologous and heterologous stimulation." (PMID 23186785, 2013). "Indeed, experimental potentiation of IL-2 signaling early on during infection promotes T-regulatory cell populations and protection against PbA CM." (PMID 23555646, 2013). "Among patients with active infection, a shift towards IL-2 or IFN-γ single-positive cells may allow distinction between patients with primary infection and cases with boosted immunity after prior contact, respectively." (PMID 24039703, 2013).
infection (continued). "IL-1alpha, IL-2, IL-10 and IL-13 mRNA levels increased similarly during infection in all groups." (PMID 24204622, 2013). "Consequently, the HCMV titers from IL-26-treated fibroblasts were about ten-fold lower than the titers reached with medium or IL-2 as control on d 4, 5, and 6 post infection." (PMID 23875025, 2013). "When cells were depleted of IL-2 24 h prior to infection, FIV production was dramatically reduced." (PMID 23201205, 2013). "Our prior studies found that SMARTA effector cells generated following Lm-gp61 infection demonstrated poor function as measured by the frequency of responders able to produce IFNγ, IL-2 and TNFα simultaneously upon restimulation and the amount of cytokine produced on a per cell basis." (PMID 23840678, 2013). "Nevertheless, IL-12Rβ1− and IL-2R− (CD25−) Th1 cells from WSX-1−/− mice (day 14 of infection) responded poorly to IL-12 and IL-2 activation, confirming the functional relevance of increased cytokine receptor expression by Th1 cells in WSX-1−/− mice (results not shown)." (PMID 23593003, 2013). "IL2 was up-regulated by 7.8 and 9.1 fold for the PT/MN/423 and TK/VA/67 infections respectively." (PMID 23521892, 2013). "Expression levels of interleukin (IL)-4, IL-10, IL-13 and tumor necrosis factor (TNF)-α were significantly up-regulated while interferon (IFN)-α, IFN-β, IFN-γ, IL-1β,IL-2, IL-3, IL-15, IL-17F, IL-18 and colony-stimulating factor (CSF)-1 were markedly decreased in PBMCs at all stages of infection." (PMID 24358317, 2013). "In addition to the cytotoxic role that CD8+ T lymphocytes play in the adaptive immune response during pathogen infection, they also simultaneously secrete some cytokines, such as IL-2, IFN-γ, and TNF-α." (PMID 22701633, 2012). "Release of IL-12 by macrophages and dendritic cells could therefore promote NK cell-mediated production of IFNγ during the early phase of infection, while IL-2 from T cells provides a potential stimulus for activation of NK cells at later stages." (PMID 22788220, 2012). "Previously we have shown that splenocytes from mice infected with HSV-IL-2 induced a TH0/TC0 type of immune response during early phase of infection suggesting that the host IL-2 may contribute to demyelination." (PMID 21364747, 2011). "As expected, infection of pig-tailed macaques with PBj-wt virus led to development of the characteristic acute enteropathic disease, accompanied by T cell activation as well as elevated IL-2 and IL-6 serum levels." (PMID 21366921, 2011). "In addition, infection of an IL-2-dependent murine cytotoxic T-cell line with a retrovirus vector carrying the human IL-2 gene resulted in factor-independent growth in vitro and tumorigenicity in vivo." (PMID 23675235, 2011). "Here, we show that chronic Plasmodium chabaudi malaria infection in mice enhances the expansion of CD4+ T cells in a second infection, and that this correlates with increased expression of the IL-2/15 Receptor beta (CD122) on memory T cells, as well as increasing IL-2 producers on re-infection." (PMID 22039531, 2011). "Interleukin 2 has been identified as an important intracellular messenger in the development of fever whether due to trauma or infection." (PMID 21961644, 2011). "After infection, cells were cultured in medium containing IL-2 for an additional 7 days." (PMID 21998586, 2011). "CD4-derived IL-2 could also help NKor CD8 T cells to clear parasites as has been shown in blood-stage infection." (PMID 21556142, 2011). "Thus, we cannot exclude the possibility that IL-2 alone increased the number of cells permissive for infection." (PMID 21819585, 2011). "IL-2 may be dispensable in this latter context where CD8+ T cells would benefit from inflammatory signals during an infection with the secretion of other factors with partly overlapping functions, such as type I interferons and IL-12." (PMID 20856822, 2010).
infection (continued). "This analysis showed that infection status was significantly associated with PCA1 (schistosome-specific antibody responses), PCA 3 (IL-10, anti-worm IgA, IgE and anti-egg IgG1) and PCA 5 (INF-γ and IL-2)." (PMID 21039611, 2010). "However there was a slight downward trend of IL-2 expression during the course of the Ts infection (P > 0.05)." (PMID 21143846, 2010). "Thus, the perforin and IL-2 functional subsets we describe herein likely serve to mediate protective immunity at different stages of infection." (PMID 20221423, 2010). "Given the low sensitivity of variants B14 and B28 to antagonism by sFc-CD134 on IL2-dependent (MYA-1) T cells, we postulated that these variants may partially escape antagonism by sFc-CD134 by utilising CXCR4 for infection." (PMID 20420700, 2010). "Here, we show for the first time that while removal of naturally-occurring Treg cells minimally affects the course of disease, increasing their numbers in vivo throughout the course of infection via IL-2/anti-IL-2 antibody complexes allows these cells to protect against ECM." (PMID 21170302, 2010). "In contrast, IL-2 levels were almostundetectable after challenge infection." (PMID 19956549, 2009). "Note the smaller scales for the cytokines in panels A and B.)Levels tended to normalize to baseline values within 3–4 weeks of infection in all animals, with IL2, IL4, IL12p40, IFNγ, and CCL3 increasing again after 6 weeks of SHIV-RT infection of the naïve animals (not statistically significant)." (PMID 20011586, 2009). "However, in terms of polyfunctionality, i.e. the co-expression of multiple cytokines such as TNF-α, IFN-γ and IL-2, we observed a difference between the two T cell populations as the infection progressed." (PMID 19529765, 2009). "Whereas, MLN cells from Se-deficient mice expressed, as expected, lower level of IFN-γ and the expression level of IL-2 was markedly lower than those secreted by MLN cells from Se-adequate mice (P<0.01) at day 14 of infection, following 24–72 h of re-stimulation." (PMID 19247447, 2009). "At 8 hours post-infection, the PBMCs were washed and cultured in medium supplemented with 5% IL-2." (PMID 18414671, 2008). "We have demonstrated that IP-10 and possibly IL-2 could be alternative or adjunct markers to IFN-γ in the diagnosis infection with M.tuberculosis." (PMID 18682747, 2008). "In addition, we observed that infection induced the upregulation of IL2 and IL4 in M." (PMID 41675929, 2026). "Although studies have reported IFN-λ and IL-2 upregulation in avian oviduct tissues following LPAIV infection, if inconsistently expressed across symptomatic birds or counterbalanced by stronger downregulation of other critical cytokines, the net outcome may still be immunosuppression." (PMID 41584795, 2025). "IL-2 stimulation induces histone acetylation at effector gene enhancers such as interferon gamma, and broader epigenetic variability, potentially shaped by factors like age, environmental exposure, or infection history, may influence NK-cell responsiveness." (PMID 40862731, 2025). "Also, interleukins like IL-2, IL-6, IL-8, and IL-12 are significant modulators of the immune system: IL-2 promotes T-cell proliferation, IL-6 acts as a pro-inflammatory cytokine, IL-8 recruits neutrophils to infection sites, and IL-12 enhances the differentiation of T-helper cells." (PMID 39684540, 2024). "In G6, IL-2, IL-12, IL-4, and IL-5, involved in the growth, proliferation, and differentiation of Th1 and Th2 cells, were notably less expressed in the early days post-infection compared to G1a, where an expression level comparable to or higher than the controls was observed." (PMID 38891666, 2024). "Also, it is possible to strengthen the association between IL-2 and the Th1 profile results in a milder form of the disease and that IFN-α and IFN-γ could be used as biomarkers for primary versus secondary infection in DENV-infected patients." (PMID 38003826, 2023).
infection (continued). "The preference for IL2 production over IFNγ in SARS-CoV-2-specific T cells in this cohort may suggest a dominant role for cross-reactive central memory CD4 T cell responses in protection from detectable infection." (PMID 36901802, 2023). "Our study found that IL-6 and IL-2 were increased significantly, while IL-10 was decreased in the Wheeze group, indicating that anti-(pro-)inflammatory factors imbalance may play a critical role in the occurrence and development of wheezing after infection." (PMID 36691058, 2023). "Moreover, in some vaccinated individuals a reduced IFN-γ T-cell response but an increased IL-2 T-cell response has been detected and may play a role in the long-term protection against infection." (PMID 36079033, 2022). "The effect of pre-infection IL-2, GROα, IFNα2, and SDF1-α on CD4 decline is likely to be independent of VL and HIV replication and instead may be reflective of pre-infection immune state that is favourable in the context of HIV disease progression once the person is infected." (PMID 35165387, 2022). "They share characteristics of effectors generated during an acute infection, having lower levels of inhibitory receptors (for example, TIM-3) and transcription factors associated with T cell exhaustion (for example, Tox) and higher levels of IFNγ and IL-2 production." (PMID 36171284, 2022). "To address this urgent unmet clinical and scientific need, we tested whether a highly sensitive, dual-colour cytokine (IFN-γ and IL-2) T cell FluoroSpot assay could determine which patients presenting with symptoms of Long COVID had evidence of past infection with SARS-CoV-2." (PMID 35772216, 2022). "The importance of IL-2 in host protection against E. acervulina infection was demonstrated in a recombinant vaccination experiment where chickens vaccinated with 3-1E recombinant protein showed enhanced protection upon challenge infection when the recombinant protein was given with IL-2." (PMID 35214673, 2022). "When we calculated the percentage of productively and latently infected cells over total infection, we found that IL-15 stimulation minimally increased the percentage of productively infected cells while decreasing the percentage of latently infected cells compared to IL-2 stimulation." (PMID 35499323, 2022). "Whereas in CPo neonates, the lack of IL-2 might be associated to surgical site infection presenting a risk for residual clefts or fistulas in the hard palate." (PMID 36466891, 2022). "Higher IL-2 responses following vaccination may be due to shorter exposure to vaccine antigen compared with persistent antigen after infection, and consequent enhanced development of uncommitted IL-2+IFNγ- memory CD4+ T-cells, although this remains to be tested." (PMID 34960185, 2021). "Increased IL-2 responses may also indicate a general enhanced development of memory T-cells following vaccination given the role of IL-2 in formation of the memory T-cell compartment, for which reason we quantified memory T-cells and their subsets after vaccination and infection using AIM assays." (PMID 34960185, 2021). "Therefore, we further speculate that consistent downregulation of the MT4 gene during SE infection in chicks may have a consequential effect on host defense response, with a potential failure to induce effective IL-2 expression." (PMID 34031125, 2021). "Multicolor flow cytometry was utilized to analyze the CD4+ and CD8+ T cell populations and their intracellular production of the cytokines IFNγ, TNF, and IL2 (single, double, and triple combinations) associated with both the lethal and nonlethal murine models of infection." (PMID 34287349, 2021).